CD4 (CD4 molecule)
Diseases named in the same sentence as CD4 in open-access papers (continued):
Sharing a sentence is not in itself a finding about the gene and the disease.
colitis (continued). "Furthermore, the intestinal CD4+Foxp3+RORγt+ Treg cells induced by gut microbiota have been shown to contribute to the suppression of gut inflammation, the inhibition of TH2-driven defense against helminths and TH2-associated colitis, and the inhibition of intestinal TH2-associated allergy." (PMID 39206204, 2024). "Combined treatment of the colitis model with thiorphan (TOP) inhibited BCM degradation by suppressing CD10 in the intestinal mucosa, activating mouse mucosal CD8, and suppressing CD4 and Treg." (PMID 39057028, 2024). "Immunofluorescence staining illustrated that UTI inhibited the infiltration of immune cells (CD4+ and CD45+) in the colon mucous contrast with the colitis group." (PMID 38397811, 2024). "During the colitis phase, cells were harvested, cultured with phorbol 12-myristate 13-acetate and ionomycin, and subsequently stained for CD3/CD4, followed by fixation, intracellular staining for IL-17A and IFNγ, and analysis using flow cytometry (FCM)." (PMID 39596393, 2024). "This colitis model elicits an immune response by releasing IL-25, activating ILC2, and producing IL-13, which activates CD4+ T cell responses, intensifying the type-2 cytokine production." (PMID 38543070, 2024). "Here, we determined a proportional enrichment of CD4+ T cells in both intraepithelial and lamina propria tissues from all DSS-colitis groups which was complemented with an increase in IL-17-producing cells." (PMID 38673843, 2024). "The results showed increased populations of CD4+ IFN-γ+ Th1 cells, CD4+ IL-4+ Th2 cells, and CD4+ IL-17+ Th17 cells in the DSS-induced colitis mice." (PMID 39595338, 2024). "Cluster-specific analysis of lymphocytes in CPI colitis demonstrated expression of Ifng across multiple T cell clusters, including TH1/TH17, cycling CD4+ T cells, cytotoxic CD8+ T cells and cycling CD8+ T cells." (PMID 37872166, 2023). "As a consequence of defective MHC II expression, the KO DCs were featured by the impaired capability to process antigen and to prime effector CD4+ T cells, thereby protecting mice from DSS-induced colitis." (PMID 37957143, 2023). "Further analysis of CD4+ T cells showed that the increase in the number of CD4+ T cells in MKO colitis mice were mainly RORγt-positive Th17 cells, which play important roles in the pathogenesis of IBD and experimental colitis." (PMID 36635421, 2023). "An activated effector population of ICOS+ cells was relatively enriched amongst infiltrating CD4+ T-cells in biopsies from both anti-CTLA-4 and anti-PD1-induced colitis compared with those from IBD patients." (PMID 36776862, 2023). "In CD4+T cells, TRIM21 degraded multiple metabolic enzymes in a proteasome-dependent manner to alleviate the onset of T cell-mediated colitis." (PMID 37249651, 2023). "T cell transfer colitis is mainly mediated by aberrantly activated T helper cells, and especially IFN-γ+ (Th1) and IL-17+ (Th17) CD4 + T cells contribute to the disease." (PMID 37311749, 2023). "Although there was no significant change in the proportional abundance of the Foxp3+ CD4+ TREG cluster between control and CPI colitis, there were a few qualitative changes in the transcriptome." (PMID 37872166, 2023). "In both CD4+ and CD8+ T cells, there was an increased expression of co-stimulatory molecules in IFNγ producing lymphocytes in CPI colitis." (PMID 37872166, 2023). "The higher representation of CD8 compared with CD4 and CD20 cells by IHC further indicated that ICI-related colitis occurred in mice." (PMID 36891304, 2023). "Fatty acid sensor GPR120 regulated IL-10 expression in the intestinal CD4+ T cells and suppressed DSS-induced colitis development in mice." (PMID 37191444, 2023). "OT-II mice deficient in RUNX3 were unable to downregulate THPOK or develop CD4+ IELs; in response to OVA exposure, they developed colitis." (PMID 37654482, 2023).
colitis (continued). "Consistent with CXCR6 being the most highly upregulated chemokine, we found that CD69+ CD103+ CXCR6+ CD4+ and CD8+ T cells were expanded in both the cLP and intraepithelial layer in mice with CPI colitis in comparison to control mice." (PMID 37872166, 2023). "Our studies into the impact of baseline TSLP expression on homeostatic CD4+ T expansion in barrier sites have revealed that colonic TSLP signaling is essential for suppressing the overexpansion of T cells and lethal colitis in adult animals." (PMID 37427591, 2023). "Therefore, in this study, we investigated whether primary and immortalized cADSCs modulated the Th cell balance in vivo and inhibited the proliferation of Th cells from mice with DSS-induced colitis in vitro and whether they inhibited canine CD4+ Th cell and CD8+ CTL proliferation in vitro." (PMID 38139314, 2023). "As a consequence of defective MHC II expression, Ubc9-/- DCs were featured by the impaired capability to process antigen and to prime effector CD4+ T cells, thereby protecting mice from DSS-induced colitis." (PMID 37957143, 2023). "In colitis mice, resveratrol treatment increases the number of anti-inflammatory regulatory T cells (CD4+FOXP3+ and CD4+IL-10+) and down-regulates the number of inflammatory T cells, such as Th1 (CD4+IFN-γ+) and Th17 (CD4+IL-17+) cells in MLNs." (PMID 35369090, 2022). "IL-2 promoted Treg cell development via AP-1 transcription factor JunB, and injection of IL-2–anti-IL-2 antibody complex in JunBfl/fl Cd4-Cre mice expanded Treg cells and alleviated DSS-induced colitis." (PMID 35237152, 2022). "To explore the pathway by which L-fucose acts on CD4+ T cells and LPMCs, we found that the mRNA levels of AHR and its target gene, CYP1A1, were significantly elevated in the colons of colitis mice by L-fucose treatment." (PMID 36432480, 2022). "Indeed, CD4+ cytotoxic T lymphocytes (CD4+ CTLs or ThCTLs) have been reported to be present in intestinal biopsies of patients with CD compared with healthy controls and in lymphopenic mice with colitis induced by adoptive transfer of naïve T cells (CD4+CD45RBhigh cells)." (PMID 35468944, 2022). "During DSS-induced colitis, IL-17A+IFN-γ+CD4+ T cell levels were significantly reduced after MNS treatment." (PMID 35784693, 2022). "Compared to control mice, the number of CD45+ cells, CD4+ T cells, and CD8+ T cells was significantly increased in mice with DSS-induced colitis, suggesting a role of CD4+ and CD8+ T cells during the development of DSS-induced colitis." (PMID 35844584, 2022). "CD4+T cells are the main T cell subset in CTLA-4-induced colitis patients, while CD8+T cells are dominant in PD-1-induced colitis." (PMID 36189293, 2022). "In the dextran sodium sulfate (DSS)-induced colitis mouse model, FMT reduces colonic inflammation and improves mucosal immune health by inducing IL-10 expressing CD4+ T cells and invariant NK T cells in the colon of mice." (PMID 36713364, 2022). "In the oxazolone-induced colitis of female BALB/C mice, nicotine (2.5 mg/kg, s.c.)attenuated inflammation by increasing the proportion of CD25+Foxp3+ Tregs and decreasing CD4+IL-17+ Tregs in colonic CD4-positive cells." (PMID 35251010, 2022). "Together, we provide evidence that CD4+ TRM cells are heterogeneous and functionally distinct regarding different subsets in DSS-induced colitis." (PMID 35844584, 2022). "The results showed that CD4+ T, CD8+ T and B220+ B lymphocytes were significantly increased in the Colitis and the Colitis/CP group, suggesting that these lymphocytes are involved in the pathogenesis of the experimental colitis." (PMID 36139127, 2022). "During steady state and disease conditions such as experimental colitis, TCR diversity and clonality of CD4+ T cells responding to gut microbiota have been determined." (PMID 36310871, 2022). "The results suggested that SSP increased the number of CD4+ TSM cells and their subsets in DSS-induced colitis." (PMID 35388299, 2022).
colitis (continued). "The extended-set feature that returned the highest AUCs in prediction of hepatitis was CD4+ TEM (AUC = 0.677), whereas colitis was weakly predicted by immature neutrophils (AUC = 0.670)." (PMID 36248910, 2022). "CD4+CD8A+ T cells in the intestine expressed IL10, which is essential for the inhibition of colitis." (PMID 36353619, 2022). "Recently, a study showed that the presence of CD4+CD69+CD103+ TRM cells was predictive of disease flares and depletion of TRM cells led to a suppression of colitis activity." (PMID 35844584, 2022). "In accordance with the contrasting effect of LysoPS on these colitis models, the number of IFN-γ–producing CD4+ T cells in the large intestine was substantially increased in Rag2−/− mice that received naive CD4+ T cells compared with DSS-treated mice." (PMID 35608941, 2022). "CD4+ T cells obtained from the mLNs of R23FR mice in remission (primed by TAM-induced IL-23 and Red 40 treatment) were used to transfer colitis to Rag1−/− mice treated with Red 40 in their drinking water (0.25 g/L) or diet (0.25 g/kg, TD.160647, diet 2019)." (PMID 35468944, 2022). "We found that CD4+ TRM cells were increased and correlated with disease activities in mice with dextran sulfate sodium (DSS)-induced colitis." (PMID 35844584, 2022). "Genetic and pharmacological inhibition of the Hh pathway was shown to intensify the severity of DSS-induced colitis in mice partly due to reduced IL-10 expression in CD45−Gli1+ stromal cells and the decreased number of CD4+Foxp3+ T cells in the colonic LP." (PMID 35563571, 2022). "We purified colonic CD4+ T cells from 3 patients with IBD (2 with CD and 1 with UC) with active colonic inflammation, treated these with NVP-2 during primary stimulation or restimulation as before, and performed RNA-seq." (PMID 35660024, 2022). "We conclude that YFP+ naïve‐like CD4+ T cells remain polarizsed to the TH1 lineage, even in in vivo in a TH1‐/TH17‐driven colitis model." (PMID 35092032, 2022). "It has been suggested that LP CD4+LAP+ T cells are involved in modulating the gut microbiota and reducing the severity of ethanol- and TNBS-induced colitis." (PMID 35954484, 2022). "Epigenetic DNA hypo-methylation of Zbtb7b activated the maturation of CD4+T cells and repressed the differentiation of DP CD4+CD8+ T cells, resulting in the production of inflammatory cytokines and colonic inflammation in UC." (PMID 35761286, 2022). "This was further supported with an increase in the mRNA expression of MHC-II in IECs from S1PR2 KO colitis mice compared to WT colitis mice suggesting that S1PR2 limits MHC-II expression and presentation to CD4+ T-cells." (PMID 36569849, 2022). "CD69−CD103− CD4+ T cells accounted for 11.7% of IFNγ-expressing CD4+ T cells in control mice and 24.8% in DSS-induced colitis." (PMID 35844584, 2022). "During the induction of colitis, IL-17A expression was notably increased in CD69+CD103− CD4+ TRM cells." (PMID 35844584, 2022). "On day 11 of DSS-induced colitis, spleen and mesenteric lymph nodes (MLN) of mice were taken to detect the percentage of CD4+CXCR5+ T cells and regulatory CD5+B cells by flow cytometry." (PMID 36172372, 2022). "Altogether, these data demonstrate that Naticol®Gut strengthens Th2 CD4 T-cell population and diminishes the activation of CD8 T cells in colon during experimental DSS-induced colitis." (PMID 34999930, 2022). "Although CD226 expression was significantly higher in CD4+ T cells from the colon than that from the spleen, CD226 expression was no changed in CD4+ T cells from the colon of mice with DSS-induced colitis." (PMID 35844584, 2022). "The infiltration of CD4+ T, CD8+ T and B220+ B lymphocytes in colon tissue were significantly increased in Colitis and Colitis/CP groups compared with the Control group (p < 0.01)." (PMID 36139127, 2022).
colitis (continued). "Cells were isolated during colitis, stimulated ex vivo with phorbol 12-myristate 13-acetate/ionomycin, then surface stained for CD3/CD4, fixed, stained for intracellular IL-17A and IFNγ and analyzed by FCM." (PMID 34983695, 2022). "Among IL-17A+ CD4+ T cells, CD69−CD103− CD4+ T cells accounted for 22.4% in control mice and 33.2% in DSS-induced colitis." (PMID 35844584, 2022). "Here, our results suggest that colitis triggered by IL-23 expression and Red 40 is dependent on IFN-γ and that IFN-γ is required for CD4+ CTL generation in R23FR mice." (PMID 35468944, 2022). "CD4+ and CD8+ cells are often found in irAEs in other organ systems, such as ICI-induced colitis, in which CD8+ cells are more predominant than in other inflammatory bowel disease." (PMID 36358686, 2022). "We showed that LysoPS confers an immunopathological profile to IFN-γ–producing CD4+ T cells through P2Y10 receptor–mediated metabolic reprogramming, which leads to colitis aggravation." (PMID 35608941, 2022). "The increase in the ratio of CD4+Nrp1+FoxP3+ cells in the lamina propria reduces disease severity in THC- and THC+CBD-treated colitis mice compared to VEH-treated colitis mice." (PMID 34298921, 2021). "Treatment with analogue 5 elevated the percentage of CD25+FoxP3+ Treg in MLN CD4 lymphocytes of mice with TNBS- and DSS-induced colitis." (PMID 33767180, 2021). "ERβ stimulation even improved colitis as demonstrated in a murine model of dextran sulfate sodium (DSS)-induced colitis, where ERB041 (an ERβ-specific agonist) led to suppression of CD4+CD25− and CD8+ T lymphocytes and restoration of Tregs balance." (PMID 34898546, 2021). "In this context, however, Garo and colleagues recently showed that specific deletion of Smad7 in DCs, as well as in CD4+ T cells, enhances TGF-β1 responsiveness and attenuates experimental colitis in mice." (PMID 33920230, 2021). "It has been reported that phages can activate IFN-γ produced by CD4+ T cells via the nucleotide-sensing receptor TLR9, which accelerates intestinal inflammation and colitis, leading to a systemic inflammation response." (PMID 34442780, 2021). "We then further investigated the effect of tiliroside on the epithelial barrier function and the proportion of CD4+ T cells, CD8+ T cell and CD19+ B cells, which have been demonstrated to play an important role in the occurrence and development of colitis." (PMID 33868286, 2021). "Although the details of the relationship between Se and IBD still need further elucidation, animal studies have found that Se can increase CD4 (+) CD25 (+) regulatory T cells and reduce Th1, Th17, and γδ T cells, thus alleviating DSS-induced colitis." (PMID 34532332, 2021). "After being treated with rTsPmy, the recruitment of the CD4+ effector T cells was significantly reduced and the pathological process of DSS-induced colitis was mitigated." (PMID 34336843, 2021). "Epithelial PBLD deficiency was associated with increased macrophage, monocyte, neutrophil, and CD4+ T cell infiltration in the CLP and MLN of mice with DSS-induced colitis, as demonstrated in our flow cytometry assays." (PMID 34059646, 2021). "In a T cell–mediated colitis mice model, oral administration of IPyA, a microbiota-derived AHR agonist, decreases the frequency of IFN-γ+ IL-10- CD4+ T cells and increases that of IFN-γ- IL-10+ CD4+ T cells in the colon lamina propria." (PMID 34966278, 2021). "Up-regulation of both IFNG and TNFA signaling pathways was identified in the CD4+ and CD8+ T cells of patients with ICI-colitis, acting on the myeloid cellular compartment." (PMID 34147519, 2021). "Flow cytometric analyses demonstrated that the proportion of Tregs among gated CD4+ T cells in the spleen, MLNs and colon was reduced in DSS colitis." (PMID 34691046, 2021).
colitis (continued). "In DSS-induced colitis, THC or THC+CBD treatments reduce polyps in colon cancer-induced mice and increase CD103+ dendritic cells and CD4+Nrp1+FoxP3+ T regulatory cells (nTregs) in the lamina propria through activation of the CB2 receptor." (PMID 34298921, 2021). "Transfer of TCRγδ +LAP+ cells ameliorate both colitis induced by the transfer of CD4+ CD45RBhigh cells to immunodeficient mice (a rodent model for Crohn’s disease) and DSS-induced colitis by expanding Foxp3+ Treg cells." (PMID 35919733, 2021). "By gating CD4+ Foxp3+ cells we observed a moderate increase in frequencies and absolute number of Tregs in the colon upon DSS-induced colitis." (PMID 34335571, 2021). "In this study, the authors used DNBS-induced colitis and showed that JTE907 treatment induced CD4 + CD25 + FoxP3 + cells in the lamina propria, which was associated with attenuation of colitis." (PMID 34298921, 2021). "Tregs, especially CD4+FOXP3+ regulatory T cells, in mouse models of colitis and allergic diarrhea can be induced by Clostridium XIVa from human microbiota." (PMID 33225985, 2020). "Significant changes in the percentages of naïve, central memory T (TCM), and effector memory (TEM) cells and their CD4+ and CD8+ subsets were found in the peripheral blood of mice with colitis using flow cytometry." (PMID 33597887, 2020). "ED amino acid treatment mitigated the colitis-induced increase in CD103+CD11b+ dendritic cells and CD4+ and CD8+ T cells and inhibited the predominant Th1/Th17 responses particularly in the colonic mucosal lamina propria of mice with colitis." (PMID 32855978, 2020). "As the two subsets of Tcm cells, CD4+CD45RA−CD62L+CCR7+ (Figures 2D1–5) and CD8+CD45RA−CD62L+CCR7+ (Figures 2E1–5) cells were downregulated after colitis mice were treated by SSP and 5-ASA for 7 days." (PMID 32714185, 2020). "Depletion of CD4 T-cells and macrophages reduced combination anti-PD-1/CTLA4 (Fc-effector)-mediated colitis and inflammation of the small intestine." (PMID 33127658, 2020). "Lymphocytes from the MLN of mice at 7 days after colitis induction were collected and stimulated with anti-CD3/CD28 antibodies to activate CD4+ T cells." (PMID 34589853, 2020). "After DSS treatment, CD4+ and CD8+ T-cells were decreased in the blood of wt mice, which is in accordance with human data from colitis patients." (PMID 32630271, 2020). "Vasoactive intestinal peptide (VIP) had therapeutic and prophylactic effects in TNBS-induced colitis, which was related to the down-regulation role of the IFN-γ level in splenic and lamina propria CD4+ T cells." (PMID 32153570, 2020). "Of note, the diminished population of IFNγ-expressing cells in the adoptive transfer colitis model was an unexpected observation, since we observed that activated NCOR1 cKOCd4 CD4+ T cells produced enhanced levels of IFNγ." (PMID 32318068, 2020). "Mouse CD4+ CAR-Treg have demonstrated efficacy in mouse models of SOT, GvHD, IPEX, colitis, allergic asthma, rheumatological diseases, and EAE." (PMID 33717052, 2020). "Both QCHS and QCHS-treated DCs improved colonic histopathology, diminished Th17 cell differentiation and inhibited IL-17 production while promoting CD4+CD25+Foxp3+ Treg differentiation and augmenting IL-10 and Foxp3 expression in colitis mice." (PMID 32967687, 2020). "It is also possible that Plac8’s effect on CD4 T cell IFNγ production occurs transiently, and the magnitude of the enhancement of the IFNγ response in Plac8-/- T cells may not be large enough to manifest during a model of chronic inflammation such as this colitis model." (PMID 32639988, 2020). "In comparison to that in the control mice, a significantly lower frequency of splenic and MLN CD4+ and CD8+ cells and Tregs, as well as splenic Th1 cells, was detected in the colitis group." (PMID 32855978, 2020).